RN7SL150P (RNA, 7SL, cytoplasmic 150, pseudogene)
Gene: Miscellaneous RNA gene on chromosome 19 (33,927,364 to 33,927,625, reverse strand). Ensembl gene ENSG00000240626.
Homologues: Orthologues: chimpanzee Metazoa_SRP (97% identical), macaque Metazoa_SRP (86% identical). Paralogues in human: RN7SL1 (73% identical), RN7SL2 (72% identical), RN7SL296P (72% identical), RN7SL3 (72% identical), RN7SL420P (71% identical), RN7SL664P (71% identical), RN7SL679P (71% identical), RN7SL431P (71% identical), RN7SL15P (70% identical), RN7SL691P (70% identical), RN7SL709P (70% identical), RN7SL769P (70% identical), and 701 more.